UBXN4 (UBX domain protein 4)
Description:
Involved in endoplasmic reticulum-associated protein degradation (ERAD). Acts as a platform to recruit both UBQLN1 and VCP to the ER during ERAD.
Synonyms: KIAA0242; UBXD2; UBXDC1; erasin
Tractability: Antibody: UniProt places it where antibodies can reach, with high confidence. PROTAC: ubiquitination databases record sites on it; its protein half-life has been measured.
Gene: Protein-coding gene on chromosome 2 (135,741,631 to 135,785,063, forward strand). Ensembl gene ENSG00000144224.
Subcellular location: Endoplasmic reticulum membrane; Nucleus envelope
Subcellular location (Human Protein Atlas): Endoplasmic reticulum
Gene Ontology:
Molecular function: protein binding
Biological process: ERAD pathway
Cellular component: endoplasmic reticulum; endoplasmic reticulum membrane; nuclear envelope
Genetic constraint (gnomAD): Loss-of-function variants: 26 observed, 46.46 expected, observed/expected ratio (o/e) 0.56, 90% interval 0.41 to 0.78. The upper end of that interval is the gene's LOEUF score, 0.78, which puts it in group 3 of 6, group 1 being the genes least tolerant of losing a copy. Missense variants: 462 observed, 537.16 expected, observed/expected ratio (o/e) 0.86, 90% interval 0.8 to 0.93. Synonymous variants: 181 observed, 185.34 expected, observed/expected ratio (o/e) 0.98, 90% interval 0.86 to 1.11.
Homologues: Orthologues: chimpanzee UBXN4 (100% identical), macaque UBXN4 (99% identical), rabbit UBXN4 (94% identical), dog UBXN4 (92% identical), pig UBXN4 (91% identical), mouse Ubxn4 (89% identical), guinea pig UBXN4 (87% identical), rat Ubxn4 (83% identical), tropical clawed frog ubxn4 (65% identical), Caenorhabditis elegans ubxn-4 (24% identical). Paralogues in human: TNRC6A (24% identical), TNRC6C (23% identical), TNRC6B (21% identical), UBXN1 (10% identical), UBAC1 (9% identical).
Diseases named in the same sentence as UBXN4 in open-access papers:
UBXN4 is named in the same sentence as 3 diseases in open-access papers, as found by Europe PMC text mining. Sharing a sentence is not in itself a finding about the gene and the disease. The quoted sentences say what the papers report.
tumor (3 papers, 2016 to 2024). "However, it remains unknown whether the remaining members of the UBXD family, such as UBXN4, UBXN11, and UBXN2B, have effects on tumour formation and progression in vitro and in vivo." (PMID 38365777, 2024).
UBXN4 also shares sentences with these, for which no sentence is quoted: cognitive decline (1 paper); keratoconus (1).